TNF (tumor necrosis factor)
Diseases named in the same sentence as TNF in open-access papers (continued):
Sharing a sentence is not in itself a finding about the gene and the disease.
multiple sclerosis (continued). "Furthermore, Huizinga and coworkers revealed that the multiple sclerosis patients with −238 GA produced lower TNF-α compared to those with −238 GG." (PMID 23577187, 2013). "Additionally, T cells are activated in multiple sclerosis and are known to secrete cytokines such as TNF-α and IFN-γ." (PMID 24090415, 2013). "Ambiguous effects of TNFα have also been demonstrated in multiple sclerosis." (PMID 21812954, 2011). "Additionally, one should keep in mind that the TNF-α system is as well involved in the development of other brain disorders such as multiple sclerosis, Parkinson’s disease and Alzheimer’s disease." (PMID 19506720, 2008). "The model was also used to dissect the molecular pathogenesis of inflammatory CNS diseases such as multiple sclerosis, by determining the effect on myelin of cytokines such as tumour necrosis factor-α (TNF-α), interleukin-1β (IL-1β), interleukin-6 (IL-6) and interferon-γ (IFN-γ)." (PMID 18793322, 2008). "Moreover, a phase II clinical study testing a recombinant TNF receptor 1 (TNFR1) immunoglobulin fusion protein neutralizing TNF (lenercept) in patients with multiple sclerosis (MS) had to be halted due to exacerbation of symptoms when compared to placebo-treated MS patients." (PMID 37138340, 2023). "The expression of inducible nitric oxide synthase (iNOS) and TNFα in microglia and the production of large amounts of nitric oxide are thought to contribute to the neuroinflammatory processes of neurodegenerative diseases such as AD, PD, multiple sclerosis, amyotrophic lateral sclerosis." (PMID 35804072, 2022). "Additionally, MTO is approved to treat different forms of multiple sclerosis as it presents immunosuppressive activity such as the inhibition of B-cell, T-cell and macrophage proliferation and a decrease in the secretion of tumor necrosis factor alpha (TNF-α) and interleukin-2 (IL-2)." (PMID 35886997, 2022). "The TNFα‐dependent pathological switch of the synaptic control from astrocytes and its deleterious consequences are observed in animal models of HIV brain infection and multiple sclerosis, conditions both known to cause cognitive disturbances in up to 50% of patients." (PMID 34904753, 2022). "In addition to paradoxical neurosarcoidosis, other neurological adverse events have been reported with the use of TNFα blockers such as multiple sclerosis, polycranial neuritis, chronic inflammatory demyelinating polyradiculoneuropathy and multifocal motor neuropathy." (PMID 24373564, 2013). "CNTF, an important promyelinating factor, inhibited inflammatory pathology in experimental allergic encephalomyelitis (EAE), a mouse model of multiple sclerosis and astrocyte-derived CNTF protected oligodendrocytes from TNFα insult." (PMID 40004040, 2025). "On the other hand, pro-inflammatory cytokines such as IL-6, IL-1β, IL-17, IL-22, TNF-α, IL-12, and IFN-γ are thought to play a pivotal role in the pathogenesis of multiple sclerosis (MS) through various signaling pathways." (PMID 40507498, 2025). "A previous study reported that walking exercises reduce TNF-α levels in obese participants, and 3-week water-walking and water-bike endurance exercises decrease TNF-α levels in patients with multiple sclerosis." (PMID 39742290, 2024). "In Multiple Sclerosis (MS), CBD in preclinical models of MS resulted in a reduction of proinflammatory cytokines such as IL-17A, IFN-γ, TNF-α, IL-6 and IL-1b and an increase in anti-inflammatory cytokines such as IL-4, IL-10 and TGF-β." (PMID 38601151, 2024). "CSF levels of TNF-α, CXCL9, and IL-6 are also elevated in other neuroinflammatory diseases such as multiple sclerosis." (PMID 37304071, 2023). "In fact, in multiple sclerosis, whose pathogenesis appears to be sustained by TNF-α, TNF-α blockade resulted in unexpected disease progression and onset of new lesions with demyelination." (PMID 29541073, 2018).
multiple sclerosis (continued). "It revealed that sildenafil can decrease the levels of TNF-α, interferon (IFN)-γ, IL-2 and IL-1β in animal model of multiple sclerosis." (PMID 28210757, 2017). "In cases of multiple sclerosis and traumatic brain injury, NAC suppressed TNF-α-mediated via downregulating the activation of nuclear factor-κB (NF-κB)." (PMID 25918547, 2015). "One of the most common adverse event of interferon beta (IFNβ) therapy for multiple sclerosis is flu-like syndrome (FLS), which has been reportedly related to increased levels of cytokines such as interleukin 6 (IL-6) and tumor necrosis factor-alpha (TNF-α)." (PMID 26285213, 2015). "Exposure to elevated levels of TNFα has also been demonstrated to elicit nuclear translocation of PAD4 isozyme in vitro, as well as in vivo, in a transgenic model of multiple sclerosis." (PMID 24762056, 2014). "The aim of this study was to investigate the changes of TNF-α, IFN-γ, and NO level in sera both in normal body temperature and after decreasing body temperature (approximately −1 degree C) in patients with multiple sclerosis." (PMID 23762603, 2013). "For example, in a model of multiple sclerosis, it is demonstrated that BDNF decreases TNF-α expression and upregulates IL-10 expression, an anti-inflammatory cytokine." (PMID 23912236, 2013). "BDNF downregulates the expression of TNF-α and upregulates the expression of IL10 in the model of multiple sclerosis." (PMID 21490702, 2010). "In vitro dTNFR is as effective as etanercept-like molecules at inhibiting TNF-α activity and has previously been shown to be therapeutic in both the CIA model and a multiple sclerosis model." (PMID 17254348, 2007). "Futher, corticosteroid-based treatments show effective anti-inflammatory efficacy as therapeutic agents for infectious diseases of the brains and in mouse model of multiple sclerosis, significantly down-regulating pro-inflammatory cytokines such as IL-1β, IL-6, IL-17, IFN-γ, and TNF-α." (PMID 40390112, 2025). "A PPARγ-mediated lenabasum response in pDCs has been shown in a multiple sclerosis model, where treatment with lenabasum resulted in a trending decrease in TNFα and IFNα, with or without CB2R inhibition." (PMID 40383862, 2025). "A retrospective study showed that IBD patients treated with TNF-α blockers showed a 43% increase in the incidence of multiple sclerosis versus patients who did not receive these agents." (PMID 36836166, 2023). "For example, the local increase of TNF-α in the hippocampal dentate gyrus activates astrocyte TNF receptor type 1, which in turn triggers persistent alterations of excitatory synapses, contributing to memory deficits in a mouse model of multiple sclerosis." (PMID 35255943, 2022). "To date, biologicals which effectively neutralize TNF activity have not shown utility for multiple sclerosis, but have had varying degrees of efficacy for other conditions." (PMID 32760383, 2020). "For instance, it has been demonstrated that TNF-alpha exhibited non-significant reductions after resistance training in individuals with multiple sclerosis." (PMID 31531060, 2019). "TNF is a pro-inflammatory cytokine that is expressed in the central nervous system and its soluble form can promote neuronal inflammation, occurring in neurodegenerative conditions such as ALS, multiple sclerosis, Alzheimer's and Parkinson's diseases." (PMID 30214903, 2018). "TNF has as detrimental role in multiple sclerosis (MS), however, anti-TNF medication is not working." (PMID 29057962, 2017). "IL-2, IFN-γ, and TNF-α levels are increased in HTLV-1 infection and contribute to neurological damage in HAM/TSP patients as well as in other neuroinflammatory conditions with clinical similarities to HAM/TSP such as Multiple Sclerosis." (PMID 23409198, 2013).
multiple sclerosis (continued). "We believe that this might be physiologically relevant, since our previous study showed that the Vav1 risk allele is associated with increased mRNA expression levels in PBMCs from healthy donors and multiple sclerosis patients, which is positively correlated to IFN-γ and TNF expression." (PMID 38565808, 2024). "Among the cytokines that could not be detected were IFN-γ, IL-17A and tumor necrosis factor (TNF)-α, which have been linked to the pathophysiology of multiple sclerosis." (PMID 36756308, 2023). "It acts through two receptors resulting in often opposing biological effects, which may explain the lack of therapeutic potential obtained so far in multiple sclerosis (MS) with non-receptor-specific anti-TNF therapeutics." (PMID 37122019, 2023). "For example, in animal models of multiple sclerosis, CBD has been shown to have a significant anti-inflammatory effect since it was able to decrease the concentration of proinflammatory cytokines interleukin 6 (IL-6), interleukin 12 (IL-12), tumor necrosis factor α (TNF-α), and interleukin 1 (IL-1)." (PMID 36289755, 2022). "Moreover, the negative patient outcomes with non-selective anti-TNF therapies suggest that the complete abrogation of TNF signaling has no beneficial effects in MS." (PMID 32733206, 2020). "Moreover, other groups also described elevated levels of IL-1β or IL-1β/TNF-α induced molecules like IL-1ra, IL-6, IL-8, IL-13, G-CSF, and Cxcl10 (IP-10) in the CSF of NMO patients, compared to the CSF of patients with multiple sclerosis or other neurological diseases." (PMID 24252536, 2013). "TNFR2 is crucial for TNF-induced regeneration of oligodendrocyte precursors that make up myelin, a finding that may be important in the treatment of multiple sclerosis and other demyelinating disorders, regardless of whether they have an autoimmune etiology." (PMID 24391650, 2013). "However, neutralization of TNFα in humans did not result in an improvement in demyelinative disease in multiple sclerosis, but rather it seemed to exacerbate it." (PMID 22271346, 2012). "In addition, the use of brodalumab may be considered in patients where TNF-alpha is contraindicated or not responsive to TNF-alpha or not appropriate, such as those patients with multiple sclerosis or congestive heart failure." (PMID 37240650, 2023). "For example, in multiple sclerosis, TNF inhibition has no therapeutic effect and could even lead to disease exacerbations, whereas TNFR1 inhibition clearly has protective effects, as we recently discovered using the Nanobody-based TNFR1-specific inhibitor, called TNF Receptor One Silencer (TROS)." (PMID 31787972, 2019). "Although clinical trials with nonselective anti-TNF-α antibodies completely failed, the role of TNF-α in the pathogenesis of multiple sclerosis is still widely debated." (PMID 34829740, 2021).
pancreatic cancer (322 papers, 2003 to 2026). "Dextran-conjugated triptolide and triptolide nano-MOFs enhance TNF-α levels, promoting an immune response that ultimately inhibits tumor progression in pancreatic cancer with KRAS mutation, while also reducing toxicity compared to free triptolide." (PMID 40490812, 2025). "Elevated levels of cytokines such as IFN-gamma, IL-6, IL-10, and TNF-alpha have been associated with an increased risk of pancreatic cancer." (PMID 39599705, 2024). "Recent studies have shown that new tumor-infiltrated M0 macrophages induce pancreatic cancer cell death via TNF-α secretion, while M1, M2, and tumor-associated macrophages do not harbor antitumorigenic activities." (PMID 37880378, 2023). "Cancer cell-induced lipolysis in adipocytes was stimulated using cancer-conditioned media (CCM) or co-culture with human pancreatic cancer cells and the cachexia-associated cytokines TNF-α and interleukin-6 in 3T3-L1 adipocytes." (PMID 35684106, 2022). "Previously, our team showed that elevated concentrations of some interleukins and TNF-α in the PB of pancreatic cancer patients were significantly associated with the number of circulating BM-derived MSCs." (PMID 35846982, 2022). "Taken together, our results suggest that loss of the LUBAC subunit Rnf31 sensitizes murine and human pancreatic cancer to CTL killing by rendering cells susceptible to caspase-8-mediated apoptosis upon TNF signaling." (PMID 35379808, 2022). "Distribution of TNF-α gene alleles among cachectic pancreatic cancer patients considering the cachexia severity." (PMID 34900737, 2021). "The addition of antibodies against IFN-γ and TNF-α during NK cell mediated differentiation of pancreatic tumors was found to restore the tumors’ susceptibility to NK cell-mediated cytotoxicity." (PMID 31878338, 2019). "The effects of IL-1 are similar to those of TNF-α, and IL1β gene promoter single nucleotide polymorphisms (SNPs) are linked with pancreatic cancer risk." (PMID 31277269, 2019). "During inflammation, cytokines and growth factors like TGF-ß1, PDGF, interleukin-1ß (IL-1ß), IL-6 and TNF-α are released in the pancreatic tumour microenvironment causing stimulation and activation of PSCs33." (PMID 30923340, 2019). "As to AP, identification of an association between the polymorphisms of TNFα and susceptibility to AP is less clear, although several SNPs in TNFα have been reported previously in both many forms of pancreatitis and pancreatic cancer." (PMID 20396411, 2010). "Additionally, TNF-α–mediated CLDN1 expression is associated with increased proliferation of pancreatic cancer cells." (PMID 37318881, 2023). "Moreover, this site was hypermethylated in non-survivors, which is consistent with previous studies that increased methylation in TNF gene was associated with poorer survival in pancreatic cancer." (PMID 35242787, 2022). "To next assess whether loss of Rnf31 also sensitizes human PDA to TNF-mediated cell death, we generated patient-derived and engineered human pancreatic cancer organoids (hPDA) with RNF31KO mutations and treated these organoids for four hours with TNF." (PMID 35379808, 2022). "Although pre-clinical evidence demonstrated reduction of pancreatic tumor-associated inflammation and desmoplasia through TNF-α inhibition, randomized clinical studies showed that modulation of TNF-alpha activity in PC patients did not produce any clinical benefit." (PMID 32659999, 2020). "Notably, some miRNA (i.e., hsa-let-7d, hsa-miR-221, hsa-miR-224, hsa-miR-23a, and hsa-miR-197) were found to be up-regulated by anti-TNFα, and are reportedly associated with pancreatic cancer." (PMID 30764482, 2019). "Another case-control study nested in the European Prospective Investigation into Cancer and Nutrition (EPIC) cohort did also not find an association between pre-diagnostic circulating CRP, interleukin-6 (IL-6), tumour necrosis factors (TNF-α) and pancreatic cancer risk." (PMID 31464604, 2019).
pancreatic cancer (continued). "Thus, TNFα deficiency abolished the effect of subdiaphragmatic vagotomy on survival in pancreatic cancer indicating that TNFα was a key mediator of vagotomy in this model." (PMID 28160574, 2017). "Therefore, our results demonstrated that MA potentiated the efficacy of TNFα susceptibility to pancreatic tumor by enhancing caspase apoptotic signaling pathway and by inhibiting NF-κB activation and its down-stream gene expression." (PMID 20367887, 2010). "Additionally, TNF‐α promoter gene polymorphisms are significantly correlated to the development of IPMNs and pancreatic cancer and might be produced and released into the microenvironment and circulation during the development and progression." (PMID 35871313, 2023). "After measuring cytokine levels (IL-6, IL-8, IL-10, IL-23, TNFα) in this group, we added these patients to our analyses, constructed ROC curves, and determined the approximate AUC values to assess the suitability of these cytokines as diagnostic markers for pancreatic cancer." (PMID 24849506, 2014). "In pancreatic cancer cell lines and pancreatic tumor samples, high expression of TNF-α has been previously reported." (PMID 41488204, 2026). "In the current study, we evaluated the effects of the secretome of human mesenchymal stem cells (hAMSCs) on Panc1 pancreatic cancer cells through the TNF-α/NF-κB signaling pathways." (PMID 41488204, 2026). "In the current study, we demonstrated the simultaneous induction of inflammation and apoptosis through the TNF-α/NF-κB signaling pathway by the secretome of hAMSCs in Panc1 pancreatic cancer cells." (PMID 41488204, 2026). "This study, focuses on investigating the effects of the secretome of human mesenchymal stem cells (hAMSCs) on Panc1 pancreatic cancer cells through the tumor necrosis factor-alpha (TNF-α)/nuclear factor-κB (NF-κB)/Caspase 3 signaling pathways." (PMID 41488204, 2026). "TNF-α induced Tyrosine dephosphorylation of the YEATS domain increases MYC eRNA binding to the YEATS2 protein in pancreatic cancer cells." (PMID 40216980, 2025). "Pparg is repressed by Hes1, which upregulates the inflammatory activity of pancreatic tumor cells in an autocrine manner, releasing inflammatory mediators, such as TNF-α, IL-6, and IL-1β." (PMID 40299348, 2025). "In our study, we demonstrate that TNF-α and IL-1β also reprogram the metabolic landscape of pancreatic cancer cells, rendering their reliance on the de novo pyrimidine synthesis pathway." (PMID 41243973, 2025). "It reduces the levels of pro-inflammatory cytokines (e.g., IL-6 and TNF-α) and pro-carcinogenic cytokines (TGF-β1, TNF-β, and CXCL12) which exerts an inhibitory effect on pancreatic cancer associated fibroblasts (CAF) and colon cancer (HCT 116) cells." (PMID 40490812, 2025). "Pancreatic tumors secrete pro-inflammatory cytokines such as IL-6 and TNF-α, which promote muscle protein degradation through the ubiquitin–proteasome pathway." (PMID 40002202, 2025). "In the immune evasion process of pancreatic cancer cells, inflammatory factors like IL-6, TNFα, and IL-10 have been found to be significantly involved." (PMID 40487760, 2025). "B7-H3-SDIE enhanced the activation of various natural killer (NK) cell subsets, induced IFN-γ and TNF secretion in the presence of B7-H3-expressing cells, and led to the effective lysis of pancreatic cancer cells." (PMID 40214484, 2025).